MET (MET proto-oncogene, receptor tyrosine kinase)
Diseases named in the same sentence as MET in open-access papers (continued):
Sharing a sentence is not in itself a finding about the gene and the disease.
melanoma (continued). "Expression of c-MET in BRAFV600E melanoma cell lines, mouse xenografts and patient tumours is further demonstrated to contribute to vemurafenib resistance under hypoxic conditions." (PMID 37181747, 2023). "This study suggests the potential values of MACC1 and MET as useful biomarkers and warrants further evaluation on larger number of melanoma cases." (PMID 37496665, 2023). "The expression of MET in canine melanoma tissue was confirmed through immunohistochemistry with a validated antibody." (PMID 37104404, 2023). "While MET inhibitors have shown some promise in controlling disease progression in human melanoma, similar targeted therapeutic options in dogs have not been investigated and remain an unmet need." (PMID 37104404, 2023). "In this study, we examined the extent of MACC1 and MET protein expression by immunohistochemical staining in a tissue microarray constructed from twenty-three melanomas and ten melanocytic nevi." (PMID 37496665, 2023). "We then evaluated the relationship between histopathologic features and MET expression for all canine melanomas." (PMID 37104404, 2023). "Abnormal expression and activation of the receptor tyrosine kinase MET is reported in many human cancers, including melanoma." (PMID 37104404, 2023). "We were able to confirm the expression of the MET protein in both melanoma cell lines, and we demonstrated MET activation by its ligand, HGF, through phosphorylation, in Western blot analysis." (PMID 37104404, 2023). "The role of HGF/MET signaling and expression of MET in melanoma has been studied more extensively than MACC1." (PMID 37496665, 2023). "Nevertheless, MET inhibitors have currently been studied, which have been proven to inhibit melanoma cell migration." (PMID 37022605, 2023). "Given the role of c-MET in melanoma invasion and migration, and its association with adhesion molecules and EMT processes, the involvement of c-MET/HGF signalling in anoikis resistance is unsurprising." (PMID 37181747, 2023). "Here we investigate the expression of MET in melanoma cell lines and tissue samples of melanoma from our clinical service and correlate the expression scores with histologic parameters, metastatic status, and survival outcomes." (PMID 37104404, 2023). "HGF/MET signaling has been recognized to have an etiopathogenetic role in melanoma progression and metastasis, as well as immune microenvironment modulation and therapeutic resistance." (PMID 37496665, 2023). "MET inhibition with Crizotinib is also effective, in a dose-dependent manner, in reducing PD-L1 expression in the melanoma SH4 and WM35 cell lines." (PMID 37444518, 2023). "Studies subsequently established that melanoma cells with high c-MET/HGF autocrine signalling have an increased propensity for metastasis to the liver." (PMID 37181747, 2023). "In this study, we aimed to investigate MET protein expression and activation in canine melanoma cell lines as well as investigate MET expression in tissue samples of canine melanoma from our clinical practice in a tertiary care academic veterinary practice." (PMID 37104404, 2023). "In this study we evaluated the expression of MET in two canine malignant melanoma (CMM) cell lines as well as in 30 CMM tissue samples that were collected from the clinical service at our institution." (PMID 37104404, 2023). "Our result was contradictive with some published studies, in which expression of HGF and its receptor c-MET has been reported to be increased in lung, colon, breast, thyroid, renal carcinoma, melanoma and various sarcomas." (PMID 37828456, 2023). "Our study shows that inhibition of MET by selective inhibitors results in a dose-dependent decrease in IFN-γ-induced PD-L1 expression in melanoma cells." (PMID 37444518, 2023). "We observed intermediate to high cytoplasmic expression of MACC1 and low to intermediate expression of MET in both melanocytic nevi and melanomas." (PMID 37496665, 2023).
melanoma (continued). "MET gene fusions also happen in melanomas, where six different N-terminal partners fused in-frame with the intracellular MET domain have been described." (PMID 37760640, 2023). "In this study, we confirmed MET protein expression in canine melanoma cell lines as well as tumor tissues." (PMID 37104404, 2023). "MC1-R is thought to play a role in melanoma progression through the activation of MET, a proto-oncogene and key regulator of metastasis in many cancers." (PMID 36499015, 2022). "Exosomes originating from highly metastatic melanoma cells have been demonstrated to educate bone marrow progenitor cells by delivering the MET oncoprotein, enhancing metastatic burden and organotropism." (PMID 36477408, 2022). "One study on BRAF and MET inhibitors in melanoma patients even showed an inferior result under the intermittent therapy compared to continuous therapy." (PMID 35273301, 2022). "The HGF/c-MET pathway plays a key role in the proliferation, survival, metastasis, and resistance of melanoma cells to MAP kinase inhibitors." (PMID 35565444, 2022). "An impact of HS levels on the activity of multiple RTKs including ERBB, FGFR, and PDGFR family members as well as AXL and MET in tumor types apart from melanoma has been described." (PMID 35798875, 2022). "We first looked at an extended list of high-risk genes predisposing to melanoma (ACD, CDKN2A, CDK4, POT1, TERF2IP, and TERT) or RCC (CDKN2B, FH, FLCN, MET, PBRM1, PTEN, SDHs, TSCs, and VHL) or both (BAP1 and MITF)." (PMID 34067022, 2021). "KCNQ1OT1 promotes cell proliferation and metastasis in melanoma by sponging miR-153, which results in the upregulation of MET oncogene." (PMID 34638331, 2021). "Inhibition of these kinases with the combination of the drugs afatinib (an ERBB family inhibitor) and crizotinib (an MET inhibitor) proved to have deleterious and synergistic effects on melanomas." (PMID 34063141, 2021). "The lncRNAs that have been associated with melanoma metastasis and their corresponding microRNA and upregulated transcripts include KCNQ1OT1/miR-153/MET, LINC00518/miR-204-5p/AP1S2, LINC00520/miR-125b-5p/EIF5A2, and UCA1/hsa-miR-125b-1/AKT1." (PMID 35008286, 2021). "Below, we will discuss different strategies tested in preclinical and clinical studies of MET inhibition alone or in combination in melanoma." (PMID 33918490, 2021). "MET expression was found to be significantly higher in metastases as compared to primary melanomas in a genomic hybridization study." (PMID 35008286, 2021). "For example, B16‐F10 metastatic melanoma cells express MET to a far greater extent than a non‐metastatic counterpart, a situation also reflected in MET expression on the respective EV populations." (PMID 33815694, 2021). "Preclinical studies have shown that enhancement of HGF/c-MET activity can increase the proliferation of melanoma cells 51, increase the invasive ability of melanoma cells 52, 53 and protect melanoma cells from apoptosis." (PMID 33746605, 2021). "Several reports indicates that ErbB and MET were found highly deregulated in melanoma patients, which made these receptors promising therapeutic targets to evaluate." (PMID 33918490, 2021). "It has been frequently represented that microRNAs inhibit many types of cancer cell invasion and migration such as cervical, breast, non-small cell lung, gastric, ovarian, melanoma, and osteosarcoma malignancies by targeting MET." (PMID 34217156, 2021). "Melanoma-specific antigens that are currently under investigation in clinical trials using CAR-T cells include c-MET, CD70, GD2 and VEGFR2." (PMID 34572949, 2021). "This study, although at lower frequency, discovered MET amplification in melanoma brain metastases as well." (PMID 34885093, 2021). "Due to several reports indicating that MET overexpression correlates with melanoma development and invasiveness, SU11274 was tested and showed efficiency inhibiting growth, enhancing apoptosis and differentiation." (PMID 33918490, 2021).
melanoma (continued). "Stimulation of the HGF/MET pathway strengthens numerous processes that are essential for melanoma development and construction of visceral metastatic niche." (PMID 34885093, 2021). "Contrary to melanocytes, it is a well-known fact that melanoma cells have the ability to express c-MET and also to release HGF, thus activating c-MET in an autocrine fashion." (PMID 34885093, 2021). "Cellular c-MET acts as an oncogene in malignant melanoma, and c-MET expression is markedly increased in melanoma cells." (PMID 32194780, 2020). "Dysregulation of the HGF/MET signaling pathway has been demonstrated in a wide range of malignancies, including malignant melanoma." (PMID 32659961, 2020). "We analyzed the expression of MET and PD-L1 in 18 human melanoma cell lines including seven primary and 11 metastatic cell lines." (PMID 32659961, 2020). "There is also further evidence that MET expression can identify patients who will develop resistance to current melanoma treatments." (PMID 32659961, 2020). "Comparative analysis of the protein content in MTEX from highly metastatic and poorly metastatic melanoma cells confirmed MET signaling as the principal mediator of BM progenitor cell “education”." (PMID 32709086, 2020). "EVs from melanoma patients consist of the melanoma-specific protein, very late antigen, tyrosinase-related protein-2, MET, caveolin-1, and Hsp70 as compared to the healthy control, rendering them a potential biomarker in melanoma." (PMID 33260606, 2020). "For example, the presence of CAV-1 in EVs from breast metastatic cells is associated with enhanced migration and invasion of recipient cells and the EV transfer of MET with melanoma metastasis to the bone marrow." (PMID 33114492, 2020). "Limited available data suggest that, in melanoma, the development of secondary mutations in NRAS or CTNNB1, overexpression of MET, and activation of the mTOR pathway by alternative mechanisms can confer acquired resistance to imatinib." (PMID 32344828, 2020). "In a murine melanoma model, adoptive T-cell transfer induced the recruitment of immunosuppressive c-MET positive neutrophils to the tumor and tumor draining lymph nodes." (PMID 32117721, 2020). "A recent large whole genome sequencing (WGS) analysis of melanomas has demonstrated relatively frequent MET aberrations, including MET gene amplification, single nucleotide variations/deletions, and structural variants." (PMID 32659961, 2020). "We therefore assessed the potential of pharmacological inhibition of c-MET in reversing anoikis resistance induced by the expression of BRN2 in melanoma." (PMID 32632141, 2020). "Simultaneously, curcumol decreased ERK phosphorylation and prevented the activity of NF-κB, thereby driving the c-MET/PI3K/AKT-dependent and ERK/NF-κB-dependent pathways associated with mouse melanoma B16 cell death." (PMID 32194780, 2020). "In summary, curcumol inhibited mouse melanoma proliferation and migration, largely by enhancing miR-152-3p and downregulating the c-MET/PI3K/AKT pathway." (PMID 32194780, 2020). "Other miRNAs (miR-34b, miR-34c, and miR-199a-3p) also contribute to this mesenchymal movement by targeting the mRNA of tyrosine-protein kinase Met (c-MET), whose increased expression facilitates melanoma cell migration and metastasis." (PMID 33203119, 2020). "Overexpression of c-MET in melanoma cells enhances cell protection from cell death and correlates with a poor clinical outcome 45,46, which was shown to be mediated by the activation of the PI3K/AKT pathways 47,48." (PMID 32194780, 2020). "It has been demonstrated that c-MET enhanced melanoma cell proliferation and invasive capacity and protected cells from apoptosis via the PI3K/AKT signaling pathway 24,30." (PMID 32194780, 2020). "It is further worth noting that the administration of exosomes with high c-MET levels facilitated metastasis of melanoma cells exhibiting lower metastatic ability." (PMID 30642077, 2019).
melanoma (continued). "Previously, we have also showed that pairs of inhibitors directed against EGFR (gefitinib, lapatinib), and MET (foretinib) are able to effectively decrease viability and proliferation, and induce apoptosis in examined melanoma cells." (PMID 31649529, 2019). "Our previous results showed that combination therapy, composed of EGFR (gefitinib or lapatinib) and MET (foretinib) inhibitors, was much more effective against melanoma cells in a comparison to a monotherapy." (PMID 31649529, 2019). "Our results for the first time indicate that combination of EGFR and MET inhibitors decrease melanoma cell migration and invasion." (PMID 31649529, 2019). "Above‐mentioned data indicate that both—EGFR and MET signalling is directly connected with melanoma cells invasion, what establishes these receptors as promising targets for anti‐cancer treatment." (PMID 31638339, 2019). "Nuclear localization of MET is found in many cancer types, for instance, melanoma, breast, hepatocellular, and prostate carcinomas suggesting a more complex and multifunctional role of MET in oncogenesis." (PMID 30700325, 2019). "Due to the involvement of EGFR and MET in melanoma progression, these receptors can be promising therapeutic targets." (PMID 31649529, 2019). "As we have previously shown, EGFR and MET seem to be promising targets for anti-melanoma combination therapy using small molecule inhibitors." (PMID 31877948, 2019). "Obtained data indicate that both EGFR and MET signalling is strictly connected with migration and invasion abilities of melanoma cells, mostly because of the regulation of their proteolytic activity and the ability to form invadopodia." (PMID 31638339, 2019). "Previously, we demonstrated that pairs of inhibitors directed against EGFR (epidermal growth factor receptor) and MET (hepatocyte growth factor receptor) trigger a synergistic cytotoxic effect in human melanoma cells, and decrease their invasive abilities." (PMID 31877948, 2019). "While treatment with BRAF- and MEK-inhibitors is not sufficient to overcome HGF-induced resistance, BRAF- and MET (the HGF receptor)-inhibitors suppress the majority of HGF-induced drug resistance in BRAF-mutant melanoma." (PMID 31067787, 2019). "In our previous work, we have already demonstrated that dual inhibition of EGFR/MET was able to elicit a synergistic cytotoxic effect in melanoma cell lines, accompanied by a decrease in their invasive abilities." (PMID 31877948, 2019). "PHA-665752, another c-MET inhibitor, inhibited the migration of NRAS-mutated melanoma cells toward HGF." (PMID 30513872, 2018). "For this reason, we decided to study the effect of an EGFR (lapatinib, gefitinib) and MET (foretinib) inhibitor combination on the viability and proliferation of selected melanoma cell lines." (PMID 29719603, 2018). "Already in the early 1990s, HGF has been shown to contribute to melanoma growth, and c-MET has been detected on melanoma cells." (PMID 30513872, 2018). "It is proposed that these melanoma TEXs promote pre-metastatic niche formation and tumor growth by overexpressing the oncogene MET within BM-derived DCs to obtain a pro-vasculogenic phenotype." (PMID 29720982, 2018). "The mechanism of HGF/c-MET signaling contribution to melanoma cell protection from apoptosis is, to some extent, similar as in melanocytes." (PMID 30513872, 2018). "HGF/c-MET signaling promotes the metastatic dissemination of melanoma cells, also through exosomes that are used for intercellular communication." (PMID 30513872, 2018). "Due to frequently reported abnormalities in the regulation of MET and ErbB protein expression among patients with melanoma, these receptors are promising therapeutic targets." (PMID 29719603, 2018). "As their expression is downregulated in melanoma, mainly by epigenetic silencing, the c-MET level is increased, leading to the enhancement of HGF/c-MET signaling." (PMID 30513872, 2018).
melanoma (continued). "Stimulation of the HGF/c-MET pathways contributes to several processes that are crucial for melanoma development, such as proliferation, survival, motility, and invasiveness, including distant metastatic niche formation." (PMID 30513872, 2018). "The role of HGF/c-MET signaling in response of melanoma to targeted therapies, and subsequent development of resistance has been investigated, which has resulted in several publications." (PMID 30513872, 2018). "Dissimilar to melanocytes, melanoma cells not only express c-MET, but also release HGF, thus activating c-MET in an autocrine manner." (PMID 30513872, 2018). "The amplification of MET, and the genomic rearrangements of MET, resulting in in-frame MET kinase fusions and c-MET activation, have been identified in melanoma." (PMID 30513872, 2018). "This review focuses on the role of HGF/c-MET signaling in melanoma with some introductory information on its function in skin and melanocytes." (PMID 30513872, 2018). "It has been demonstrated in preclinical studies that the enhanced activity of HGF/c-MET can activate the proliferation of melanoma cells, increase their invasive capacity, and protect melanoma cells from apoptosis." (PMID 30513872, 2018). "From an opposite perspective, the role of the HGF/c-MET pathway in the progression of several tumors, including melanoma, stimulates research towards the development of inhibitors of this pathway." (PMID 30513872, 2018). "An emerging body of data implicates the tyrosine kinase MET in mediating resistance to BRAF inhibitors in BRAFV600E mutant melanoma." (PMID 28147313, 2017). "In context with our finding that MYSM1 bound to the c-MET promoter region in close vicinity to PAX3 in melanoma cells, our data indicate that MYSM1 is an epigenetic regulator of melanoma growth and potentially promising new target for tumor therapy." (PMID 28978033, 2017). "Firstly, our data indicate that MYSM1 participates in the regulation of genes involved in melanoma survival and proliferation, such as c-MET, via functional interaction with the sequence-specific TF PAX3." (PMID 28978033, 2017). "Another important finding of our study was the identification of GH regulation of the autocrine hepatocyte growth factor (HGF) and its cognate receptor MET (or c-MET) on the four melanoma cell lines supporting and adding to recent observation." (PMID 28223541, 2017). "Other members of the miR-34 family, miR-34b and miR-34c, were reported to regulate the expression of natural killer cell receptor ligand ULBP2, a prognostic marker in human melanoma, as well as MET, cyclin-dependent kinases, and N-myc expression." (PMID 28396701, 2017). "In line with a function of MYSM1 in the regulation of c-MET in melanoma cells, c-MET mRNA expression was significantly decreased in A375 cells lentivirally silenced for MYSM1 in comparison with scrambled control A375 cells." (PMID 28978033, 2017). "In a survey of 40 malignant melanoma specimens, MET expression and activation were evident in 88% and 21% of cases, respectively." (PMID 28103611, 2017). "Our in vitro drug studies confirmed that high level of HGF/MET signaling correlates with low sensitivity to a BRAF(V600E) inhibitor in melanoma." (PMID 28453553, 2017). "In the old situation within specialised hospitals, we assumed that multiple single-gene tests were performed, minimally three for NSCLC patients (a multigene panel, HER2/EGFR, and ALK, ROS, RET, or MET) and two for melanoma patients (BRAF and NRAS or KIT)." (PMID 27899957, 2016). "They further showed that exosome-mediated metastasis was dependent on expression of MET in exosomes, and that MET protein was increased in exosomes found in patients with advanced melanoma." (PMID 26826285, 2016). "The MART-1+ xMD-selected melanoma cells demonstrated a substantial increase in BRAF and MET mutation frequency compared to the macrodissction of the admixture." (PMID 26999048, 2016).